IGHA2 (immunoglobulin heavy constant alpha 2 (A2m marker))
Description:
Constant region of immunoglobulin heavy chains. Immunoglobulins, also known as antibodies, are membrane-bound or secreted glycoproteins produced by B lymphocytes. In the recognition phase of humoral immunity, the membrane-bound immunoglobulins serve as receptors which, upon binding of a specific antigen, trigger the clonal expansion and differentiation of B lymphocytes into immunoglobulins-secreting plasma cells. Secreted immunoglobulins mediate the effector phase of humoral immunity, which results in the elimination of bound antigens. The antigen binding site is formed by the variable domain of one heavy chain, together with that of its associated light chain. Thus, each immunoglobulin has two antigen binding sites with remarkable affinity for a particular antigen. The variable domains are assembled by a process called V-(D)-J rearrangement and can then be subjected to somatic hypermutations which, after exposure to antigen and selection, allow affinity maturation for a particular antigen. Ig alpha is the major immunoglobulin class in body secretions.
Tractability: Antibody: its Gene Ontology location is reachable by antibodies, with high confidence; UniProt places it where antibodies can reach, with medium confidence; UniProt predicts a signal peptide or a membrane-spanning region. PROTAC: ubiquitination databases record sites on it.
Gene: Immunoglobulin constant (C) gene on chromosome 14 (105,583,731 to 105,588,395, reverse strand). Ensembl gene ENSG00000211890.
Subcellular location: Secreted (Isoform 1); Cell membrane
Pathways (Reactome):
Hemostasis: Cell surface interactions at the vascular wall
Vesicle-mediated transport: Scavenging of heme from plasma
Gene Ontology:
Molecular function: immunoglobulin receptor binding; antigen binding
Biological process: antibacterial humoral response; glomerular filtration; positive regulation of respiratory burst; adaptive immune response; B cell receptor signaling pathway; complement activation, classical pathway; immune response
Cellular component: blood microparticle; extracellular exosome; extracellular region; monomeric IgA immunoglobulin complex; secretory dimeric IgA immunoglobulin complex; secretory IgA immunoglobulin complex; IgA immunoglobulin complex; immunoglobulin complex, circulating; plasma membrane
Homologues: Orthologues: mouse Igha (61% identical). Paralogues in human: IGHA1 (93% identical), IGHM (32% identical), IGHG1 (29% identical), IGHG3 (29% identical), IGHE (28% identical), IGHG2 (28% identical), IGHG4 (28% identical), IGHD (25% identical), IGLL1 (12% identical), IGLL5 (12% identical), IGLC1 (10% identical), IGLC2 (10% identical), and 65 more.
Diseases named in the same sentence as IGHA2 in open-access papers:
IGHA2 is named in the same sentence as 23 diseases in open-access papers, as found by Europe PMC text mining. Sharing a sentence is not in itself a finding about the gene and the disease. The quoted sentences say what the papers report.
breast carcinoma (5 papers, 2020 to 2022). "IGHA1 and IGHA2 mRNA levels are highly correlated and are associated with improved prognosis with a higher immune activity in breast cancer." (PMID 35281270, 2022).
COVID-19 (3 papers, 2020 to 2023). A disease caused by infection with severe acute respiratory syndrome coronavirus 2. "Components of this multimer are clearly overexpressed in the colostrum of COVID-19 patients, like the alpha heavy chain (IGHA2) or immunoglobulin kappa proteins." (PMID 37628421, 2023). "Additional profiling of immune response-related genes highlighted the preferential proximal PAS usage of immunoglobulin genes, such as IGHM, IGHG1, IGHG3, and IGHA2, especially in B cells and plasma cells of COVID-19 samples." (PMID 34376223, 2021). "There was also an increase in the mean CDRH3 length of the BCRs in the COVID-19 patients, that was most pronounced in the IGHA1, IGHA2, and IGHG1 isotype subclasses." (PMID 33384691, 2020). "The significantly increased usage of IGHA1 observed in the COVID-19 patients is in line with mucosal responses, where the longer hinge in IGHA1 compared to IGHA2 may offer advantages in antigen recognition by allowing higher avidity bivalent interactions with distantly spaced antigens." (PMID 33384691, 2020).
myeloma (2 papers, 2021 to 2022). "The translocation involved a rearrangement between MYC and the IGHA2 switch region developing at a relatively early stage of disease; post-initial immortalization but before clinical myeloma." (PMID 33436579, 2021). "Interestingly, myeloma patients with IgA depletion had a significant downregulation of immunoglobulin heavy constant alpha 1 and 2 (IGHA1 and IGHA2) when compared to patients with normal and elevated levels of IgA." (PMID 35800053, 2022).
Achalasia (1 paper, 2016). A disorder of esophageal motility characterized by the inability of the lower esophageal sphincter to relax during swallowing and by inadequate or lacking peristalsis in the lower half of the body of the esophagus. "Genes implicated in innate defense against pathogens, like CXCL17, IGHA1, and IGHA2, were down-regulated in patients with achalasia." (PMID 27511445, 2016).
atherosclerosis (1 paper, 2023). A disease characterized by the build-up of fatty material and calcium deposition in the arterial wall resulting in partial or complete occlusion of the arterial lumen. "Another study additionally revealed that measuring the plasma level of IGHA2, encoded by IgA, might be a valuable biomarker in detecting subclinical atherosclerosis." (PMID 37762221, 2023).
Autoimmunity (1 paper, 2022). The occurrence of an immune reaction against the organism's own cells or tissues. "We found that autoreactive IGHV4-34 BCRs, which are elevated in autoimmunity, were significantly depleted in IGHD/M but elevated in class-switched B cells, most notably for the IGHA2 and IGHG2 B cells consistent with class-switching of these autoreactive B cells during the response to SARS-CoV-2." (PMID 35216673, 2022).
esophageal squamous cell carcinoma (1 paper, 2022). Esophageal squamous cell carcinoma (ESCC) is a type of esophageal carcinoma (EC) that can affect any part of the esophagus, but is usually located in the upper or middle third. "IGHA2 is significantly associated with the OS of patients with esophageal squamous cell carcinoma, as evaluated using a prognostic risk score model of immune-related genes." (PMID 36158689, 2022).
influenza (1 paper, 2024). An acute viral infection of the respiratory tract, occurring in isolated cases, in epidemics, or in pandemics; it is caused by serologically different strains of viruses (influenzaviruses) designated A, B, and C, has a 3-day incubation period, and usually lasts for 3 to 10 days. "Reanalysis of prior PBMC RNA-seq data on influenza vaccine responses in younger adults showed upregulated expression of IGHG1 and IGHG3 at day 7, whereas pneumococcal vaccines upregulated the expression of IGHA2 and IGHG2." (PMID 38182669, 2024).
triple-negative breast carcinoma (1 paper, 2022). An invasive breast carcinoma which is negative for expression of estrogen receptor (ER), progesterone receptor (PR), and human epidermal growth factor receptor 2 (HER2). "In the light of prognosis, IGHA2 is tied in with basal-like and triple-negative breast cancer." (PMID 35333898, 2022).
tumor (6 papers, 2020 to 2025). "The data further indicate that the expression levels of IGHG1 mRNA are more associated with an active immune response in the tumor than IGHA2 mRNA." (PMID 32656317, 2020). "To take another approach to estimate the relation of IGH mRNAs with processes in the tumor we performed correlation analyses of IGHA2 and IGHG1 mRNAs with all other mRNAs, expressed as log2 of the FPKM, obtained with the Tuxedo RNA-Seq analysis pipeline." (PMID 32656317, 2020). "The IGHA2 mRNA levels correlate with metagenes for these cell types, which may imply that the markers represent the same characteristics in the tumor." (PMID 32656317, 2020). "In contrast, tumor samples from PTC patients with concurrent HT occupied the majority of TAMs and IGHA2+ plasma cells." (PMID 34805166, 2021).
infection (2 papers, 2016 to 2022). The state of being infected such as from the introduction of a foreign agent such as serum, vaccine, antigenic substance or organism. "IGHA1 and IGHA2 are protein-coding genes that may serve both to defend against local infection and to prevent access of foreign antigens to the immune system." (PMID 27511445, 2016). "For example, IGHA2 and IGHG2 were significantly increased after vaccination while they were not significant changed after infection." (PMID 35686122, 2022).
cancer (1 paper, 2020). A tumor composed of atypical neoplastic, often pleomorphic cells that invade other tissues. "Furthermore, IGHG1 mRNA levels, which were not as strongly associated with prognosis in basal-like cancers, display a higher correlation with immune cell metagenes than IGHA2 mRNA." (PMID 32656317, 2020).
IGHA2 also shares sentences with these, for which no sentence is quoted: breast tumor (2 papers); Amoebiasis (1); colorectal cancer (1); dilated cardiomyopathy (1); gynecological tumors (1); melanoma (1); Primary immunodeficiency (1); prion disease (1); staphylococcus aureus infection (1); systemic lupus erythematosus (1); vitamin D deficiency (1).